MMP2 (matrix metallopeptidase 2)
Diseases named in the same sentence as MMP2 in open-access papers (continued):
Sharing a sentence is not in itself a finding about the gene and the disease.
pneumoconiosis (3 papers, 2015 to 2025). An occupational lung disorder caused by inhalation of dust particles. "The observed trend is likely to be driven by advancements in technologies in pneumoconiosis diagnostics, including the emergence of validated biomarker (e.g., KL-6, MMP-2) and the continuous evolution of AI-assisted imaging analysis systems for pneumoconiosis." (PMID 40900707, 2025).
Polypoidal choroidal vasculopathy (3 papers, 2013 to 2022). The presence of aneurysmal 'polypoidal' lesions in the choroidal vasculature. "However, increases in MMP2 and MMP9 were correlated with polypoidal choroidal vasculopathy, suggesting potentially different underlying mechanisms from AMD." (PMID 36498929, 2022).
pulmonary edema (3 papers, 2005 to 2021). Accumulation of fluid in the lung tissues causing disturbance of the gas exchange that may lead to respiratory failure. "Lidocaine that was administrated half an hour earlier could significantly reduce the activity of MMP-2/9 and alleviate pulmonary edema." (PMID 34804364, 2021). "It has been observed that MMP-2 and MMP-9, two most crucial MMPs in the lung are over-expressed in pulmonary edema, suggesting that MMPs may become a potential target for pulmonary edema treatment." (PMID 34163357, 2021).
retinal degeneration (3 papers, 2015 to 2017). Degeneration of the retina. "The expression of macrophage markers (CD14 and MAC-1), neutrophils (Ly6G), monocyte chemoattractant protein (MCP-1), angiogenesis marker (VEGF) and matrix metalloproteases (MMP-1 and MMP-2) were also upregulated in retinal degeneration models CBA/J and NOD.SCID-rd1." (PMID 28258056, 2017). "Furthermore, MMP-2 activity/expression was reported to remain unchanged in other retinal degeneration models such as excitotoxic injury, ischemia-reperfusion (IR) injury or optic nerve transection." (PMID 27893855, 2016). "Importantly, 6 of 7 phototransduction mutants underwent retinal degeneration with the exception of mmp2 mutant, which is correlated with the theory that most phototransduction mutations ultimately result in photoreceptor cell death." (PMID 26659849, 2015).
rosacea (3 papers, 2022 to 2024). A chronic erythematous skin disorder that affects the face. "Among the different types of MMPs, MMP-2 and -9 have been implicated as participants in the pathogenesis of rosacea." (PMID 36077255, 2022). "MMP2 and MMP9 are associated with the pathogenesis of rosacea, with elevated MMP-9 mRNA levels in rosacea patients’ facial skin." (PMID 39351216, 2024). "Laboratory benchmark testing for this disease is not useful, therefore, we aimed to evaluate the gingival crevicular fluid (GCF) levels of extracellular metalloproteinases (MMP)-2 and MMP-9 as novel rosacea biomarkers." (PMID 36077255, 2022). "This manuscript aims to compare the GCF levels of MMP-2 and MMP-9 in systemically healthy and rosacea patients and to evaluate their potential use as novel disease biomarkers." (PMID 36077255, 2022). "Previous studies have shown that the expression of MMP2 and MMP9 is increased in rosacea skin." (PMID 39692542, 2024). "In this study, we hypothesize that rosacea influences the GCF levels of MMP-2 and -9 regardless of periodontal status and thus can be used as a novel diagnostic biomarker for rosacea." (PMID 36077255, 2022). "Also, we could not quantify the levels of MMP-2 in the GCF of rosacea patients and healthy subjects due to MMP-2 concentrations being below the range detection limit (86.6 pg/mL) awarded by the kit." (PMID 36077255, 2022).
salivary gland tumors (3 papers, 2014 to 2020). "Studies have shown that the expression of MMP-2 and -9 is linked with the biological behavior of salivary gland tumors." (PMID 31936364, 2020). "In the present study, immunohistochemical expression of P63, maspin and MMP-2 were assessed in MEC and ADCC, two most common malignant salivary glands tumors with various cellular differentiations." (PMID 32582823, 2020). "Accordingly, the aim of the present study was to determine and compare the expression of P63, maspin and MMP-2 in MEC and ADCC, two common salivary gland tumors with various cellular differentiation and structures." (PMID 32582823, 2020).
serous ovarian cancer (3 papers, 2020 to 2024). "Studies have shown that MMPs influence tumor cell migration, invasion and metastasis, particularly in advanced ovarian serous cancers, and a correlation between MMP2 expression and OC progression has been established." (PMID 38311733, 2024). "While high MMP-2 and MMP-9 expression have been associated previously with neo-angiogenesis and tumor vascularization, an increase in protein expression of MMP-9 correlated with an increase in patient’s death rate diagnosed with high-grade serous ovarian cancer." (PMID 35047406, 2021). "In addition, increased expression levels of MMPs, including MMP-2, MMP-7, and MMP-9, as well as TIMPs, including TIMP-1 and TIMP-2, were observed in mucinous ovarian cancer compared with those in serous ovarian cancer." (PMID 32197606, 2020). "Even though the TCGA datasets from three studies on 1680 serous ovarian carcinomas suggests a prognostic utility (OS and PFS) of MMP-14 based on its altered and unaltered genetic expression in serous ovarian cancer patients, no such links could be made with TIMP-1, -3 or MMP-2, -9, and -11." (PMID 35047406, 2021).
sleeping sickness (3 papers, 2015 to 2021). "In sleeping sickness, for instance, an increase in MMP-2 and MMP-9 favors leukocyte penetration into brain parenchyma, and parasite load and inflammation intensity in canine leishmaniosis." (PMID 33891967, 2021). "In some studies, the increasing levels of MMP-2 and MMP-9 correlated with the presence of parasites and leukocytes in the cerebrospinal fluid (CSF) of Trypanosoma brucei gambiense infected patients with the final stage of African sleeping sickness." (PMID 30572657, 2018).
soft tissue sarcoma (3 papers, 2013 to 2021). A malignant neoplasm arising from muscle tissue, adipose tissue, blood vessels, fibrous tissue, or other supportive tissues excluding the bones. "Furthermore, increased secretion of MMP2 and MMP9 correlated with metastatic potential in bone and soft tissue sarcomas." (PMID 35145908, 2021).
systemic sclerosis (3 papers, 2007 to 2021). A chronic disorder, possibly autoimmune, marked by excessive production of collagen which results in hardening and thickening of body tissues. "We previously demonstrated the increased gelatinases (MMP2 and MMP9) activity in bleomycin-induced systemic sclerosis, and MMP9 was the main gelatinase in the lung tissues." (PMID 34912332, 2021). "In tears, however, we observed significantly higher levels of MMP-2/TIMP-1, -2 which indicates an imbalance in the MMP/TIMP system towards an increased breakdown of matrix proteins in the visual organ during systemic scleroderma." (PMID 33218057, 2020). "Based on these results, we speculate that MMP-9, MMP-2, TIMP-2, and VEGF/sVEGFR-2 may play an important role in ischemic retinal degeneration or retinal reorganization in systemic sclerosis." (PMID 33218057, 2020).
testicular embryonal carcinoma (3 papers, 2015 to 2025). A malignant germ cell neoplasm arising from the testis. "MEHP, a metabolite of DEHP, was found to activate MMP2 expression to induce the invasion and migration of human testicular embryonal carcinoma cells." (PMID 39990676, 2025). "Results from this present study demonstrate that PPARβ/δ attenuates tumor progression in testicular embryonal carcinoma, in part, through interfering with RARα signaling and suppressing MMP2-mediated cell invasion and migration." (PMID 26431381, 2015).
thyroid tumor (3 papers, 2018 to 2020). A benign or malignant neoplasm affecting the thyroid gland. "MMP2 is involved in the invasion of thyroid tumor cells, and its expression is regulated by the ERK and JNK pathways." (PMID 33381460, 2020).
tuberculosis (3 papers, 2011 to 2025). A chronic, recurrent infection caused by the bacterium Mycobacterium tuberculosis. "Tuberculosis (TB) of the central nervous system (CNS) is a deadly disease characterized by extensive tissue destruction, driven by molecules such as Matrix Metalloproteinase-2 (MMP-2) which targets CNS-specific substrates." (PMID 21569377, 2011). "Serum cytokines/inflammatory mediators (especially MMP-2, OPN, BAFF, and multiprotein combinations) show significant potential in diagnosing childhood tuberculosis, effectively distinguishing infection status and providing new directions for developing childhood-specific TB diagnostic tools." (PMID 41007639, 2025).
urothelial bladder carcinoma (3 papers, 2006 to 2022). "To further validate the TSP4, MMP2, and MMP9 associations in human BC tumours, we analysed the correlations among TSP4, MMP2 and MMP9 expression in human BC tumours by analysing The Cancer Genome Atlas (TCGA) database for urothelial bladder carcinoma datasets on the GEPIA2 web server." (PMID 34142438, 2021). "To further validate the correlations among ATG5/12, Beclin 1, MMP2, and MMP9 in BC, we analyzed urothelial bladder carcinoma datasets on the GEPIA2 web server." (PMID 35449123, 2022).
uterine prolapse (3 papers, 2022 to 2025). Downward displacement of the UTERUS. "The results indicated that the occurrence of uterine prolapse was positively correlated with age, postmenopausal age, and MMP-2 and MMP-9 expression (p < 0.01), and negatively correlated with CD44 expression (p < 0.05)." (PMID 35910471, 2022). "The occurrence of uterine prolapse was positively correlated with age, postmenopausal age, and MMP-2 and MMP-9 expression (p < 0.01) and negatively correlated with CD44 expression (p < 0.05)." (PMID 35910471, 2022). "Additionally, a direct link between heightened MMP‐2 expression and uterine prolapse was found, suggesting that variations in MMP‐2 levels contribute to the onset and progression of POP." (PMID 40159633, 2025). "Oxidative stress is involved in POP, especially uterine prolapse, through direct regulation of the ECM or post-transcriptional regulation of MMP-2 by isoprostanes." (PMID 37731721, 2023). "One study showed that the level of isoprostanes was higher in the fibroblasts of the main ligament and urine samples of women with uterine prolapse than in women without uterine prolapse, and MMP-2 mRNA expression in the main ligament of patients with uterine prolapse significantly increased." (PMID 37731721, 2023).
uveitis (3 papers, 2018 to 2022). An inflammatory process affecting a part of or the entire uvea. "Elevated levels of MMPs were found in the aqueous humor of uveitis patients, in correlation with the inflammatory activity, and it was shown that specific inhibition of MMP-2 and -9 ameliorates EAU." (PMID 32183784, 2020). "In the clinical setting, only MMP-2 was found in the control group, while higher levels of MMP-2 and -9 were detected in patients with higher uveitis activity." (PMID 29686615, 2018). "Although the mechanism of sIL-2R elevation in uveitis is still unknown, MMP-2 and MMP-9 may be involved in the migration of lymphocytes in uveitis as well as IOL." (PMID 36357882, 2022). "Furthermore, MMP-2, as an activating sheddase of TNF-α, facilitates the secretion of active TNF-α, contributing to the chronicity of uveitis." (PMID 29686615, 2018). "Vitreous MMP-2 was significantly higher in the IOL with extraocular involvement group than in both the IOL without extraocular involvement group and uveitis groups (P < 0.05)." (PMID 36357882, 2022). "Vitreous MMP-2 levels were not elevated in either the IOL and uveitis groups in this study, whereas vitreous MMP-9 levels in the uveitis group were significantly higher than in the IOL group." (PMID 36357882, 2022). "Vitreous MMP-2 was not significantly different between the IOL group (2.3 ± 0.79 ng/ml) and the uveitis group (2.5 ± 0.58 ng/ml, P = 0.42), whereas vitreous MMP-9 was significantly lower in the IOL group (1.0 ± 1.07 ng/ml) than in the uveitis group (8.3 ± 7.04 ng/ml) (P < 0.05)." (PMID 36357882, 2022).
Varicose veins (3 papers, 2014 to 2017). Enlarged and tortuous veins. "Active MMP-1 and total MMP-2 concentrations were significantly decreased in varicose veins while the tissue inhibitors of metalloproteinases (TIMP -1 and -2), were significantly increased, probably explaining the increased collagen content found in LDv." (PMID 24505358, 2014). "Similar mechanism could explain the significant decreases of MMP-2 and -9 observed in varicose veins." (PMID 27362269, 2016). "On the contrary, it has been demonstrated that in varicose veins decreased MMP-1 and MMP-2 activities could result in accumulation of collagens and thickening of the vascular wall." (PMID 27362269, 2016). "Our results describe a decrease in active MMP-1, total MMP-2 (while total MMP-1 is not modified in varicose veins) and an increase in TIMP-1 and TIMP-2 concentrations in varicose veins." (PMID 24505358, 2014).
vasculitis (3 papers, 2021 to 2024). "MMP-2 and MMP-9 have considerably higher levels in plasma samples of RA patients with vasculitis than from those without vasculitis." (PMID 37998356, 2023).
viral hepatitis (3 papers, 2013 to 2023). An acute or chronic inflammation of the liver parenchyma caused by viruses. "However, only a few studies have evaluated CK-18 M30 and MMP-2 levels in CHB patients.Two important features should be considered in noninvasive markers used to determine the fibrosis levels of chronic viral hepatitis." (PMID 24032040, 2013).
viral myocarditis (3 papers, 2013 to 2022). Myocarditis that is caused by an infection with a viral agent. "Besides, suppression of uPA, MMP-2, and MMP-9 have been demonstrated to attenuate the remodeling and dysfunction of the left ventricle after acute pressure overload or viral myocarditis." (PMID 32354131, 2020). "The same outcome was observed in vivo in a viral myocarditis model, and furthermore, Ad-IL-17AR:Fc intervention decreased MMP-2 significantly without significantly changing TIMP-1 expression." (PMID 23977238, 2013).
Acanthamoebiasis (2 papers, 2018 to 2023). "Additionally, increased expression and activity of matrix metalloproteinases -2 and -9 (MMP-2 and MMP-9) were observed in the kidneys of hosts with systemic acanthamoebiasis." (PMID 38041167, 2023).
Achalasia (2 papers, 2018 to 2020). A disorder of esophageal motility characterized by the inability of the lower esophageal sphincter to relax during swallowing and by inadequate or lacking peristalsis in the lower half of the body of the esophagus. "The increased serum levels of gelatinases prompted us to investigate achalasia tissues as a possible source of MMP-2 and MMP-9." (PMID 30449890, 2018). "On zymography analysis, EJOO patients had lower MMP-9 levels compared to both achalasia patients and healthy controls and lower MMP-2 levels compared to controls." (PMID 30449890, 2018). "In many inflammatory diseases, the ratio of MMP-9 versus MMP-2 is a useful marker, as was corroborated here in achalasia versus controls." (PMID 30449890, 2018). "MMP-9-positive and MMP-2-positive cells were more abundant in achalasia (n = 49) versus control biopsies from transplant donors (n = 10)." (PMID 30449890, 2018). "Overall, basal MMP-2 levels were lower in achalasia in comparison with control levels and the ratio of MMP-9 versus MMP-2 was increased in achalasia." (PMID 30449890, 2018). "The percentages of MMP-9‒expressing cells were significantly higher in patients with achalasia when compared with those producing MMP-2." (PMID 30449890, 2018). "The data suggest that the ratio MMP-9/MMP-2 might be useful as novel serum marker for achalasia." (PMID 30449890, 2018). "Distinctly higher ratios of MMP-9/MMP-2 and activated MMP-9/proMMP-9 are found in the sera of achalasia patients than the controls, and MMP-9 can be used as an innate immune effector for binding to novel substrates in achalasia." (PMID 31947787, 2020). "Ratios of MMP-9/MMP-2 and act/proform MMP-9 of EJOO patients were similar as observed in healthy controls, in contrast to the significant increase observed in achalasia patients versus healthy controls." (PMID 30449890, 2018). "The presence of MMP-2 and MMP-9 proteoforms was analyzed in sera of two cohorts of achalasia patients." (PMID 30449890, 2018). "We showed significantly increased ratios of MMP-9/MMP-2 and activated MMP-9/proMMP-9 in sera of achalasia patients (n = 88) versus controls (n = 60)." (PMID 30449890, 2018).
actinic keratosis (2 papers, 1999 to 2025). A precancerous lesion of the skin composed of atypical keratinocytes. "The results of the previous part of this research indicate that MMP-2 expression is more intense in lesions of actinic keratosis compared to normal tissues and to keratoacanthoma or Bowen’s disease lesions, inversely proportional to the histopathological degree of dysplasia." (PMID 40724562, 2025). "Following the histopathological diagnosis of keratoacanthoma, Bowen’s disease and actinic keratosis, the biological preparations were deparaffinised and homogenised in order to perform the FRET technique using the “MMP-2 Assay Kit Fluorometric”." (PMID 40724562, 2025).
age (2 papers, 2020 to 2024). A temporal measurement of the time period elapsed since an identifiable point in the life cycle of an organism. "Oxidative stress regulates the expression and activity of MMP-2 and has been well-recognized as a contributing factor to age-related pathogenesis." (PMID 38534403, 2024). "Of these, Mmp2 and Mrc2 are reduced in atria after 2 weeks of exercise which is of particular interest because these genes are also reduced in the age-related fibrosis of multiple tissues and AF is strongly linked to aging." (PMID 33424629, 2020).
Airway obstruction (2 papers, 2014 to 2023). Obstruction of conducting airways of the lung. "Previous studies showed an association between MMP-2 level and airway obstruction." (PMID 25427655, 2014). "Interestingly, we found that MMP-2 level at T18 was significantly associated with the severity of airway obstruction (FEV1/FVC, p = 0.02, 95% CI [0.11;0.86] and was lower in GOLD D patients compared to GOLD A patients (7.8 ± 2 105 AU vs 12.8 ± 0.13 105 AU, p = 0.04)." (PMID 25427655, 2014).
alcoholic liver diseases (2 papers, 2017 to 2020). A disorder caused by damage to the liver parenchyma due to alcohol consumption. "Overexpression of the miR-34a also upregulates the expressions of matrix metalloproteinase 2 and 9 (MMP2 and MMP9) in alcoholic liver diseases." (PMID 28680559, 2017).
amyotrophic lateral sclerosis (2 papers, 2021). Amyotrophic lateral sclerosis (ALS) is a neurodegenerative disease characterized by progressive muscular paralysis reflecting degeneration of motor neurons in the primary motor cortex, corticospinal tracts, brainstem and spinal cord. "In an in vitro model of amyotrophic lateral sclerosis (ALS), PACAP treatment of motor-neuron like cells mitigated cell death with its mechanism of action being the epidermal growth factor receptor (EGFR) and matrix metallopeptidase-2 (MMP-2) axis." (PMID 33653014, 2021).
and T-cell lymphomas (2 papers, 2013 to 2022). "MMP-2 was negatively immunolabelled in lymphocytes of control lymph nodes, whereas B-cell and T-cell lymphomas exhibited minimal to moderate amount of MMP-2." (PMID 23641796, 2013). "Interestingly, in T-cell lymphomas MMP-2 qRT-PCR analysis revealed a significant positive correlation with TIMP-2." (PMID 23641796, 2013). "Significant correlations between MMP-2 and TIMP-2 (p<0.001; Spearman r=0.82) and between MMP-9 and VEGF-A (p<0.01; Spearman r=0.67) were found in T-cell lymphomas." (PMID 23641796, 2013).
Arterial thrombosis (2 papers, 2022 to 2025). The formation of a blood clot inside an artery. "Platelets also release MMP-2, and in in vivo arterial thrombosis models as well as collagen-dependent whole blood perfusion experiments, platelet-associated MMP-2 promoted thrombus formation by amplifying platelet activation." (PMID 36422558, 2022).